FOXM1 (forkhead box M1)
Diseases named in the same sentence as FOXM1 in open-access papers (continued):
Sharing a sentence is not in itself a finding about the gene and the disease.
cancer (continued). "Down-regulation of the chemokine CXCR4 gene, known to be involved in cisplatin resistance, dissemination of peritoneal metastasis and development of cancer-initiating cells in several cancer, including EOC, was another special feature of OSPC2 cells induced by FOXM1 loss." (PMID 28482906, 2017). "In addition, many studies have shown the importance of FoxM1 in the tumorigenesis of several cancer types, and its overexpression is closely involved in tumor development and progression." (PMID 28767320, 2017). "Besides, the combined treatment decreased β-catenin/FOXM1 interaction and reduced the cancer stem cell subpopulation in CRC cells, as indicated their diminished capacity to form colonospheres." (PMID 28423516, 2017). "Also of note is the presence of different FOXM1 isoforms, with FOXM1b exclusively expressed in cancer cells and FOXM1c with enhanced transforming potential." (PMID 28498805, 2017). "However, deregulated FOXM1 signalling in cancer is involved in cell migration, invasion, angiogenesis, stem cell renewal, DNA damage repair and cellular senescence, which impact tumor initiation, progression, metastasis, angiogenesis and drug resistance." (PMID 28427178, 2017). "These evidences suggest that dysregulated of FOXM1 expression and FOXM1 signal pathway in tumor microenvironment may serve as a key factor in human cancer development." (PMID 28427178, 2017). "Furthermore, previous studies indicate that FOXM1 induces chemotherapy resistance in various cancer cells by protecting cancer cell proliferation and abrogating apoptosis." (PMID 27494877, 2016). "FOXM1 level is the most common differentially expressed gene in the majority of cancers, including oral, esophageal, lung, breast, kidney, and bladder cancer, as compared to normal tissues, suggesting a possible role in cancer initiation." (PMID 27385468, 2016). "Current data suggest that targeting FOXM1 in mono- or combination therapy may have promising therapeutic benefits for the treatment of cancer." (PMID 27542221, 2016). "In addition, FOXM1 is found to increase resistance to chemotherapy drugs in multiple types of cancer." (PMID 27034162, 2016). "The dysregulation of the PI3K/Akt/FOXO3a axis may lead to drug resistance by enhancing DNA repair, as well as cancer cell maintenance, proliferation and survival through overexpression of FOXM1." (PMID 28040803, 2016). "To resolve this issue, we have previously developed a molecular method, the qMIDS assay, by exploiting the aberrant expression of a key oncogene FOXM1 shown to be amongst the top upregulated oncogenes across 39 cancer types and is a major predictor of poor cancer prognosis." (PMID 27409343, 2016). "In this regard, the activation of SIRT1 in FOXM1 overexpressed tumors may prove to be a potential weapon in fighting these types of cancers." (PMID 27542221, 2016). "The overexpression of FOXM1 has been found in various types of cancers." (PMID 27542221, 2016). "Moreover, expression of FOXM1 is correlated with a clinically aggressive, drug-resistant, cancer phenotype and poor patient survival." (PMID 26918606, 2016). "Inhibiting FOXM1 acetylation or increasing its deacetylation activity by the activation of SIRT1 may provide an efficient strategy to fight FOXM1 overexpressed cancers." (PMID 27542221, 2016). "The FOXM1 transcription factor plays a significant role in the regulation of a multitude of biological processes, including cell proliferation, oxidative stress, angiogenesis, cancer development, and drug resistance." (PMID 27542221, 2016). "Numerous articles have reviewed that FOXM1 function as oncogene and could be a therapeutic target in many kinds of cancer." (PMID 27716361, 2016). "Furthermore, several studies indicates that FoxM1 plays an important role in the resistance of cancer cells to gefitinib." (PMID 27494877, 2016). "Accordingly, FOXM1 serves as a dominant role in proliferation of cancer cells." (PMID 27034162, 2016).
cancer (continued). "The critical role of FOXM1 in cancer affirms its significance for therapeutic intervention." (PMID 27542221, 2016). "Given that FOXM1, GLUT1 and HK2 play instrumental roles in cell proliferation and aerobic glycolysis of cancer cells, we sought to determine the underlying mechanisms that may be responsible for coexpression of these three biomarkers." (PMID 27351131, 2016). "Besides its essential roles in cell cycle regulation, FOXM1 also emerged as an oncogenic transcription factor with a high expression and functional impact in many types of cancer cells." (PMID 27351131, 2016). "Because different cancer types express high levels of FOXM1, FOXM1 anti-oxidant activity could be a mechanism through which cancer cells escape premature senescence and apoptosis." (PMID 27385468, 2016). "Small molecules, which interfere with the nucleophosmin-FOXM1 interaction, decrease levels of FOXM1 and may be effective in treating cancer." (PMID 27074562, 2016). "LDH-5 is composed of four LDH-A units which is overexpressed in many cancers including PDAC as a result of post-translational or transcriptional c-Myc, K-Ras, HIF-1α, and FOXM1 (forkhead box protein M1) dependent regulation, and is associated with poor prognosis." (PMID 26164081, 2015). "FOXM1 is overexpressed in a number of human cancers including GBM." (PMID 25852826, 2015). "Importantly, 64% of the FOXM1 target genes exhibited highly correlated expression with FOXM1 across cancer samples (R values >7)." (PMID 25889361, 2015). "FOXM1 is located at chromosome 12p13.33, a known amplified region in cancer." (PMID 26243836, 2015). "Our results reveal widespread co-ordinate deregulated expression of the FOXM1 regulatory network in OAC, including changes in both co-regulators (eg LIN54) and target genes (eg UHRF1) which have potential diagnostic utility in identifying late-stage cancer." (PMID 25889361, 2015). "However, compared to what is known about the role of FOXM1 in cancer, its function in a physiological epithelial system remains to be fully understood." (PMID 26121260, 2015). "For example, FOXM1 upregulation induced genomic instability in normal human keratinocytes, and FOXM1 is a member of a conserved gene expression profile for genomic instability in human cancer." (PMID 26243836, 2015). "Consistent with the real-time PCR analysis, the down-regulation of FoxM1 expression significantly enhanced E-cadherin expression and attenuated Vimentin and Snail expression in FoxM1-knockdown SW620 cancer cells compared with those of control cells at the mRNA levels." (PMID 25935853, 2015). "Previous groups have demonstrated FOXM1 over-expression in cancer." (PMID 26576650, 2015). "FOXM1 has been reported to be overexpressed in various cancers and may be a suitable target for immunotherapy." (PMID 26640950, 2015). "Increasingly more recent cancer therapies often involve blockade of multiple pathways using a combination of therapeutic agents and it may be that targeting FOXM1 pathways will prove a useful treatment adjunct." (PMID 26576650, 2015). "FOXM1 is a key regulator of over 200 genes involved in cancers." (PMID 26299613, 2015). "FOXM1 is a proto-oncoprotein that is overexpressed in various types of cancer." (PMID 25537512, 2015). "Previous studies have implicated FOXM1 and MYBL2 overexpression in a range of different cancers." (PMID 25889361, 2015). "FDI-6 needs additional validation, as concerns have been raised about its specificity, and its potency may require improvement for possible treatment of FOXM1-dependent cancers." (PMID 26243836, 2015). "FOXM1 is therefore considered to be a suitable target for anti-cancer immunotherapy." (PMID 26640950, 2015). "With the gradual deepening of the study, FOXM1 may become an important target for cancer therapy in the future." (PMID 26451068, 2015).
cancer (continued). "Previous studies have indicated that the transcription factor FOXM1 is commonly upregulated in this cancer type but the impact of this overexpression on gene expression in the context of OAC is largely unknown." (PMID 25889361, 2015). "FOXM1 can not only promote the formation of tumor by increasing cell proliferation ability, but also enhance tumor metastasis and invasion activity in advanced cancer." (PMID 26451068, 2015). "Similarly, BRCA1 and CHEK2 were suggested to participate in cancer development by modulating DNA repair and cell cycle checkpoints in collaboration with FOXM1 and E2F1, respectively." (PMID 26001967, 2015). "The human forkhead box protein M1 (FoxM1) gene, consisting 10 exons, is mapped to chromosome 12p13-3, and plays important roles in cellular proliferation and differentiation during embryogenesis and development of cancer." (PMID 26264222, 2015). "Furthermore, novel molecular functions for FOXM1 have been identified in cancer cells beyond simply the acceleration of G2–M phase progression." (PMID 26576650, 2015). "Next, we conducted an MEK siRNA analysis to determine whether FOXM1 could be a suitable target for anti-cancer immunotherapy." (PMID 26640950, 2015). "Importantly, we provide evidence for co-upregulation of FOXM1 and PLK1 expression in these cancers as predicted from their co-regulatory association." (PMID 26576650, 2015). "We aimed to show that there is a relationship of PLK1 to FOXM1 in cancer samples." (PMID 26576650, 2015). "Given that our previous observation that the D150 residue of MELK is required for the interaction of MELK protein with the oncogenic transcriptional factors c-JUN and FOXM1 in a cancer-specific manner, it is likely that the kinase domain is essential for MELK-driven GSC survival." (PMID 24739874, 2014). "Overall, our data suggest that targeting FOXM1 in tumors with FOXM1 inhibitors individually or in combination with other anticancer drugs may have strong therapeutic potential against cancer." (PMID 25093142, 2014). "Next, we found that the structurally similar thiazole antibiotic thiostrepton also inhibits the transcriptional activity and FOXM1 expression, and they both induce strong apoptosis in human cancer cells of different origin that correlates with suppression of FOXM1." (PMID 25093142, 2014). "However, more studies are indeed needed to expand our understanding of how SUMOylation influences FOXM1 activity in cancers." (PMID 24918286, 2014). "Indeed, FOXM1 overexpression has been documented in cancers of the lung, breast, liver, prostate and colon, etc. suggesting that FOXM1 has a key role in tumorigenesis." (PMID 25411964, 2014). "Furthermore, FOXM1 also promotes cancer progression by facilitating cancer angiogenesis, invasion and metastasis." (PMID 25287128, 2014). "Deregulation of FOXM1 has been documented in various cancers." (PMID 25411964, 2014). "Furthermore, we demonstrated that human cancer cell lines with FOXM1-KD became more sensitive to ROS-induced cell death than original cell lines." (PMID 25093142, 2014). "FOXM1 has gained much attention and become a subject of intense research in the cancer field." (PMID 24918286, 2014). "Therefore, targeting FOXM1 (the relay center for cancer development and a potential prognostic marker) holds a promising therapeutic intervention." (PMID 24918286, 2014). "Since bortezomib is already in the clinic and the ROS inducer PEITC is in clinical trials, our data suggest that induction of ROS and inhibition of FOXM1 by these drugs may be used for cancer patients." (PMID 25093142, 2014). "Unlike the other FOX-transcription factors, FOXM1 is associated with cell proliferation and is overexpressed in cancer." (PMID 24824601, 2014).
cancer (continued). "The FOXM1 transcription factor is upregulated in the majority of human cancers, indicating that it may participate in the initiation of human carcinogenesis." (PMID 24959264, 2014). "Particularly FOXM1 sustains proliferation, evades action of tumor suppressors, increases resistance of cancer cells to apoptosis, induces replicative immortality, stimulates angiogenesis, contributes to invasion and metastasis, and enables genomic instability and inflammation." (PMID 25093142, 2014). "We suggested that FOXM1 might be “the Achilles' heel of cancer” and an attractive target for cancer treatment." (PMID 25093142, 2014). "Furthermore, knockdown of NPM in human cancer cells led to suppression of FOXM1, indicating that NPM controls levels of FOXM1 in cancer cells." (PMID 25093142, 2014). "Upregulation of FOXM1 expression is an early event during cancer development." (PMID 25287128, 2014). "In addition, the 14-3-3σ sub-network was predicted to regulate FOXO signaling and FOXM1 transcription factor networks that are known marker regulators of cancer progenitor populations and metastasis." (PMID 23741479, 2013). "Moreover, increased level of FOXM1 coincided with metastasis of many cancers, and FOXM1 had been suggested as a predictor of poor prognosis in cancers." (PMID 23762558, 2013). "FoxM1 has a well characterized role in cell cycle progression through regulation of the G1/S and G2/M phases of cell cycle, but has also been characterized as an oncogene, with aberrant expression in a variety of cancers." (PMID 23857410, 2013). "In addition to its positive role on cell proliferation, FoxM1 has been shown to play roles in other cancer-related processes, such as invasion and metastasis." (PMID 23467617, 2013). "In addition to this, recent studies have placed FoxM1 in DNA damage response and senescence pathways, two pathways relevant to tumor progression and the response to cancer therapies." (PMID 23467617, 2013). "FoxM1 is a promising and attractive target for cancer therapy." (PMID 23467617, 2013). "Importantly, FoxM1-/- MEFs and FOXM1-depleted cancer cells have difficulty undergoing mitosis and exhibit chromosomal instability and polyploidy." (PMID 23386997, 2013). "Moreover, FoxM1 was found to be overexpressed in many different types of human cancer, suggesting a role of FoxM1 in tumor proliferation." (PMID 23467617, 2013). "Because overexpression of FoxM1 has been demonstrated to lead to deregulated cell growth, and FoxM1 has been found being overexpressed in many cancers, it has been frequently argued that targeting FoxM1 may provide an opportunity towards curbing tumorigenesis." (PMID 23857410, 2013). "Taken together, abrogation of FOXM1 signaling may provide multidirectional approaches for controlling cancers including GBM." (PMID 23404835, 2013). "This notion is clearly supported by the wealth of information accumulated demonstrating that FoxM1 is involved essentially in most, if not all, processes associated with cancer progression." (PMID 23857410, 2013). "FoxM1 has been proposed to be involved with uncontrolled cell division in early stages of tumorigenesis, and increased expression of FoxM1 remarkably correlates with progressive cancer stages." (PMID 23857410, 2013). "Taken together, FoxM1 is a promising and attractive target for cancer therapy." (PMID 24204899, 2013). "FOXM1 is abundantly expressed in a wide range of human cancers, suggesting that targeting FOXM1 could be a therapeutic strategy against human malignancies." (PMID 22393369, 2012). "The establishment of FoxM1 as a STAT3 gene target could connect STAT3 signaling to cancer-related cellular processes, such as increased proliferation, survival and drug resistance." (PMID 23110199, 2012).
cancer (continued). "FoxM1, a master regulator of mitotic gene expression, is required for cell proliferation and its inhibition leads to reduction in anchor-independent growth and tumorigenesis of cancer cells." (PMID 22900969, 2012). "Finally, to increase our understanding of the role FoxM1 in our cancer model, we analyzed the overall gene expression changes in FoxM1-depleted K562 cells." (PMID 23110199, 2012). "Therefore, understanding intrinsic FoxM1 regulation and function has become an important target to better comprehend cancer cell proliferation, progression and drug resistance." (PMID 23110199, 2012). "Convincing evidence has shown that FoxM1 is upregulated in a wide variety of malignant tumors." (PMID 23006512, 2012). "Additionally, FoxM1 is directly related to cells that have high proliferation rates, such as embryonic and cancer cells, but is mainly expressed in solid tumors." (PMID 23110199, 2012). "Because FoxM1 silencing inhibited the expression and activity of MMP-2, MMP-9 and VEGF that are thought to be critically involved in the processes of tumor cell migration, invasion and metastasis, we tested the effect of FoxM1 deletion on cancer cell migration and invasion." (PMID 23006512, 2012). "FoxM1 has been suggested to be crucial to cell cycle progression in other cancer cells." (PMID 23110199, 2012). "In addition, Forkhead Box M1 (FOXM1) has been identified as an oncogenic transcription factor which is frequently upregulated in numerous human cancers." (PMID 23285101, 2012). "We thus proposed that FOXM1 overexpression might stem from constitutively activated ERK signaling that contributes to the metastatic capability in cancer cells." (PMID 21858223, 2011). "Higher expression of FoxM1 was noted in many types of human cancers." (PMID 21857934, 2011). "This indicates that upregulation of FOXM1 may be an early molecular signal required for aberrant cell cycle and cancer initiation." (PMID 20187950, 2010). "The close link between FoxM1 repression and induction of apoptosis suggests that the thiopeptides may exert their proapoptotic activity at least partially through the inhibition of FoxM1 in human cancer cells." (PMID 19440351, 2009). "Whilst the FOXM1 gene is now widely accepted to be a commonly upregulated oncogene in majority of human solid cancers, its role and mechanism in cancer initiation and progression remain unclear." (PMID 19287496, 2009). "Our bioinformatics analysis on published microarray data on various other types of human premalignant lesions and primary cancers confirmed that FOXM1 gene is commonly upregulated in a number of premalignant tissues supporting its ubiquitous role in early oncogenesis." (PMID 19287496, 2009). "Since thiazole antibiotics suppress the expression and the activity of FoxM1 and at the same time FoxM1 overexpression protects cancer cells from Siomycin A and thiostrepton toxicity, FoxM1 may be a valid target of thiazole antibiotic-induced apoptosis." (PMID 19440351, 2009). "FOXM1 is a gene of interest because recently chemical inhibitors of FOXM1 were described to limit proliferation and induce apoptosis in cancer cells in vitro, indicating that FOXM1 inhibitors could represent useful anticancer therapeutics." (PMID 18254960, 2008). "In addition, recent studies have documented FOXM1 in cancer therapy resistance." (PMID 41714589, 2026). "However, FOXM1 is aberrantly high-expressed in the majority of human cancers." (PMID 41714589, 2026).